JAK2 (Janus kinase 2)
Diseases named in the same sentence as JAK2 in open-access papers (continued):
Sharing a sentence is not in itself a finding about the gene and the disease.
eosinophilia (43 papers, 2012 to 2026). "In contrast, BCR::ABL1 or tyrosine kinase fusions associated with myeloid/lymphoid neoplasms with eosinophilia, as well as JAK2, MPL, and CALR mutations, are used as exclusion criteria." (PMID 38992589, 2024). "This case report presents a rare clinical manifestation of a myeloid/lymphoid neoplasm with eosinophilia (MLN-eo) with PCM1::JAK2 rearrangement that initially presented as B-cell acute lymphoblastic leukaemia (B-ALL)." (PMID 41530508, 2026). "Both the World Health Organization (WHO) and the International Consensus Classification (ICC) have updated the former category of “Myeloid/Lymphoid Neoplasms Associated with Eosinophilia and Rearrangement of PDGFRA, PDGFRB, FGFR1, or PCM1::JAK2”." (PMID 41530508, 2026). "Rarely, MS cases with Janus kinase 2 (JAK2) mutation and FIP1L1::PDGFRA gene fusion with eosinophilia occur." (PMID 39996833, 2025). "Myeloid (and lymphoid) neoplasms with eosinophilia are associated with rearrangement of the tyrosine kinase (TK) genes, namely PDGFRB, PDGFRA, FGFR1, JAK2, FLT3, and ABL1 (excluding BCR-ABL1)." (PMID 39156600, 2024). "The JAK2-rearranged eosinophilia displays an unfavorable clinical course with a rapid progression from chronic to acute leukemia." (PMID 33418988, 2021). "The presence of +9/+9p chromosomal abnormalities in the context of AML with eosinophilia may be a clue for cryptic JAK2 structural rearrangements." (PMID 38337573, 2024). "This category name has changed from the previous “myeloid/lymphoid neoplasms with eosinophilia and rearrangement of PDGFRA, PDGFRB or FGFR1, or with PCM1::JAK2” (MLN-eo), to specify the underlying molecular genetic changes and to include cases with ETV6::ABL1, FLT3 fusions or other TK fusion genes." (PMID 37454239, 2023). "Eosinophilia and thrombocytosis workup was performed to exclude other reasons, and it was unremarkable, including lactate dehydrogenase (LDH), immunoglobulin E (IgE) level, BCR/ABL (breakpoint cluster region, Abelson murine leukemia), JAK2 tyrosine-protein kinase mutation, ova, and parasite." (PMID 41477390, 2025). "Myeloid or lymphoid neoplasms with eosinophilia can demonstrate gene rearrangements in PDGFRA, PDGFRB, FGFR1, JAK2, or FLT3 or ETV6::ABL or other tyrosine kinase gene fusion (MLN-TK)." (PMID 38611061, 2024). "Cases of AML with JAK2 and FLT3 rearrangements are also included in the current WHO classification in the category of “myeloid/lymphoid neoplasms with eosinophilia and tyrosine kinase gene fusions”." (PMID 38337573, 2024). "Among the alterations found in primary Eosinophilia, gene fusions involving PDGFRα, PDGFRβ, FGFR1 or JAK2 represent the biomarkers of WHO-defined "myeloid and lymphoid neoplasms with eosinophilia"." (PMID 34772467, 2021). "The frequency of eosinophilia varied significantly depending on the specific fusion gene involved: it was present in 91% of patients with FIP1L1::PDGFRA and 100% with ETV6::ABL1, but only in 43% of those with PDGFRB, FGFR1, or JAK2 fusion genes." (PMID 41530508, 2026). "While basophilia and eosinophilia, particularly in combination, are more typical for BCR::ABL1pos CML, elevated hemoglobin/hematocrit and the presence of normoblasts in PB are more typical for JAK2 V617Fpos MPN." (PMID 40681596, 2025). "Eosinophilia workup was done to rule out the common causes, including LDH, IgE, ova and parasite, BCR/ABL mutation, and JAK2 mutation, and they all returned negative." (PMID 41477390, 2025). "Several other gene rearrangements involving JAK2 (located on chromosome 9p24) and FLT3 (located on chromosome 13q12) may rarely manifest as AML with clonal eosinophilia." (PMID 38337573, 2024). "In the case of eosinophilia, FISH/cytogenetics and molecular analysis (on bone marrow aspirate or peripheral blood cells) should specifically look for PDGFRA, PDGFRB, FGFR1, FLT3, ETV6, and JAK2 gene rearrangements." (PMID 37274287, 2023).
eosinophilia (continued). "Our study showed that all 11 CEL patients carrying the F/P gene exhibited more intense phosphorylation of JAK2 than the other eosinophilia cases without this fusion gene." (PMID 22523564, 2012). "Western blot results showed that phosphorylated JAK2 proteins were present at higher levels in F/P(+) CEL patients than in other eosinophilia patients lacking the F/P fusion gene or healthy volunteers." (PMID 22523564, 2012). "After ruling out the hypothesis of non−hematologic origin, testing for gene rearrangements associated with clonal eosinophilia, such as BCR::ABL1, PDGFRA, PDGFRB, FGFR1, PCM1::JAK2, and JAK2::V617F, did not yield any definitive clues." (PMID 38992589, 2024). "If either PDGFRA, PDGFRB, FGFR1, or JAK2::PCM1 gene rearrangement is identified, the diagnosis should be classified as “myeloid or lymphoid neoplasms with eosinophilia and tyrosine kinase gene fusions”; eosinophilia may be a clue to this alternative diagnosis." (PMID 38067330, 2023). "In 81/135 (60%) evaluable patients, hypereosinophilia (>1.5 × 109/l) was observed in 40/44 (91%) FIP1L1::PDGFRA and 7/7 (100%) ETV6::ABL1 positive patients but only in 13/30 (43%) patients with PDGFRB, FGFR1, and JAK2 fusion genes while 9/30 (30%) patients had no eosinophilia." (PMID 37454239, 2023). "Eosinophilia is present in almost all cases of MLN-TK, caused by fusion genes involving a receptor [PDGFRA or B, fibroblast growth factor receptor (FGFR), fms like tyrosine kinase 3 (FLT3)], a transcription factor (ETV-6), or a non-receptor kinase (Janus kinase 2, JAK2)." (PMID 37274287, 2023). "Nearly 100 different TK fusion genes, involving at least six TK (PDGFRA, PDGFRB, FGFR1, JAK2, ABL1, FLT3), have been identified in distinct MLN with or without eosinophilia." (PMID 39037514, 2024). "To date, more than 70 different TK fusion genes with recurrent involvement of at least six TK (PDGFRA, PDGFRB, FGFR1, JAK2, ABL1, FLT3) have been identified in clinically and morphologically distinct MLN with or without eosinophilia." (PMID 37454239, 2023). "In contrast, it was only observed in 13/30 (43%) patients with PDGFRB, FGFR1 or JAK2 fusion genes Absence of eosinophilia was restricted to 9/30 (30%) patients with PDGFRB, FGFR1 and JAK2 fusion genes." (PMID 37454239, 2023).
glioblastoma (43 papers, 2010 to 2026). The most malignant astrocytic tumor (WHO grade IV). "Up-regulation of JAK2 could reflect a pro-proliferative role within the glioblastoma cells as they react to the growth inhibition caused by down-regulation of the PI3K pathway." (PMID 32946518, 2020). "In this study, Jak2/Stat3 expressions were examined for the first time in the glioblastoma cell line (U87) after a separate and combined application of NP and DX." (PMID 39459502, 2024). "Since it can suppress Jak2/Stat3, an important cancer cell proliferation pathway in glioblastoma, the combination of NP and DX can be used as an alternative treatment agent." (PMID 39459502, 2024). "In subsequent experiments, we confirmed that SRPK1 can participate in the malignant progression of glioblastoma by regulating the Wnt/β-catenin and JAK-2/STAT-3 pathways." (PMID 38397980, 2024). "In NSCLC and glioblastoma, anlotinib played an anticancer role by inducing apoptosis and autophagy through the JAK2/STAT3 pathway." (PMID 39508048, 2024). "Vehicle control, NP and DX agents were applied individually and in combination with glioblastoma cells; the U87 cell line and Jak2 and Stat3 gene expressions were detected after 48 h." (PMID 39459502, 2024). "JSI-124 has been identified as a trigger for apoptosis in glioblastoma cells through the modulation of the JAK2/STAT3 signaling pathway." (PMID 38001999, 2023). "g., IFNGR1, JAK1, and JAK2) made glioblastoma cells more resistant to CAR T cells both in vitro and in vivo." (PMID 36389701, 2022). "Activated p-JAK2 was significantly increased in irradiated glioblastoma cells whereas the iPA+IR combined treatment strongly reduced the JAK2 phosphorylation." (PMID 31993371, 2019). "Other studies have further supported the essential role of the JAK2/STAT3 signaling for EGFRvIII-driven glioblastoma cell migration and invasion by promoting focal adhesion and stabilizing the EGFRvIII/JAK2/STAT3 axis." (PMID 30279357, 2018). "Here, we have identified the Jak2 small molecule inhibitor G6 as a potential therapy for Jak2-dependent glioblastoma." (PMID 25162558, 2014). "The role of Jak2 signaling in glioblastoma tumors has only recently been investigated, so the clinical significance of Jak2 inhibition is still unclear." (PMID 25162558, 2014). "Collectively, these results indicate that G6 has discernible therapeutic efficacy in glioblastoma cells that express active Jak2." (PMID 25162558, 2014). "Our results contained herein provide additional evidence of a role for Jak2 signaling in glioblastoma cells and the potential application of Jak2 inhibitors for GBM therapy." (PMID 25162558, 2014). "We found that the T98G glioblastoma cell line expresses a high level of active Jak2 (ie, pJak2), and that treatment with G6 reduced Jak2/STAT3 phosphorylation in a dose-dependent manner." (PMID 25162558, 2014). "Here, we initially examined expression of Jak2 protein in three glioblastoma cell lines; namely, A172, U87MG, and T98G." (PMID 25162558, 2014). "Specifically, in 2007, constitutive phosphorylation of Jak2 was found in the GL15 glioblastoma cell line, and treatment with tyrphostin AG490, a pan tyrosine kinase inhibitor, was shown to induce cell cycle arrest in these cells." (PMID 25162558, 2014). "TROP2 activates the JAK2/STAT3 pathway to promote metastasis in glioblastoma cells." (PMID 34067437, 2021). "Because iPA may affect Jak2/Stat5 pathways involved in the transcription of RAD51 we next depleted STAT5a/b in glioblastoma cells by RNAi and tested the mRNA levels of RAD51." (PMID 31993371, 2019).
glioblastoma (continued). "Interestingly, chromatin immunoprecipitation assays in HT-1080 cells demonstrated that PIBF binds the promoter regions of IL-6, an overexpressed cytokine in glioblastomas that acts as a ligand of the JAK2/STAT3 pathway." (PMID 28168193, 2017). "Using PTEN-deficient glioblastoma cell line U87MG-EGFRvIII screening and U87MG-PTEN counter-screening, we have previously reported that G5-7 selectively blocked Janus kinase 2 (Jak2), preventing GBM proliferation." (PMID 34925034, 2021). "Overall, these results represent another evidence that the inhibition of JAK2-STAT5a/b signaling by iPA might provide a possible adjuvant therapy for irradiation of glioblastoma, enhancing the sensitivity to radiation and reducing radiation-induced damage to the neighboring tissues." (PMID 31993371, 2019). "Therefore, the JAK2/STAT3 may represent a potentially important target for therapy of EGFRvIII-positive glioblastoma." (PMID 30279357, 2018). "The transient receptor potential cation channel, subfamily M, member 7 (TRPM7) also leads to increased cancer stem cell proliferation in glioblastoma multiforme (GBM) through activation of the JAK2/STAT3 and/or Notch signaling pathways." (PMID 28219421, 2017). "U87MG glioblastoma cells display a coordinated survival response upon LY-294002 treatment, involving both PI3K and JAK2." (PMID 32946518, 2020). "To dissect further the STAT5 signaling cascade, we evaluated he phosphorylation state of the Janus Kinase (JAK2), the prototypical upstream kinase responsible for STAT5 phosphorylation in glioblastoma cells treated with iPA+IR." (PMID 31993371, 2019). "The activation of JAK2/STAT3 pathway, which is overactivated in glioblastomas, promotes cell migration and invasion in several types of cancer." (PMID 28168193, 2017). "Expression of active Jak2 and/or STAT3 has been observed in a number of immortalized glioblastoma cell lines and primary cells." (PMID 25162558, 2014). "In the initial studies examining the role of Jak2 in glioblastoma, the tyrphostin compound, AG490, was used to block Jak2 activation." (PMID 25162558, 2014). "Recently, Cucurbitacin I was shown to inhibit JAK2/STAT3 and induce autophagy and apoptosis in glioblastoma cells in vitro and in flank xenograft studies." (PMID 25237832, 2014). "IL-20 treatment also induced the activation of Jak2/Stat3 and ERK1/2 pathway in GBM8901 glioblastoma cells." (PMID 22962576, 2012). "In malignant glioblastoma cell lines, the levels of phosphorylated JAK1, JAK2, and STAT3 were uniformly upregulated with FAK and positively correlated, followed by the levels of phosphorylated p38, JNK and ERK1/2 downregulated, and the trend was reversed after treatment." (PMID 38240856, 2024). "Furthermore, in addition to affecting the JAK2/STAT3 pathway, JSI-124 was also found to activate the NF-κB pathway to induce apoptosis in human glioblastoma cells." (PMID 38001999, 2023). "In addition, another recent study showed that Jak2/STAT3 signaling is essential in the migration, invasion, and tumor progression of EGFRvIII glioblastoma cell lines." (PMID 25162558, 2014).
Insulin resistance (42 papers, 2011 to 2025). Increased resistance towards insulin, that is, diminished effectiveness of insulin in reducing blood glucose levels. "Ablating Jak2 in the myeloid compartment reduces insulin resistance in obese mice, which is associated with a decrease in infiltration of adipose tissue macrophages (ATMs)." (PMID 40801626, 2025). "Among adipocytokines, leptin is associated with insulin resistance via shared signaling pathways—such as JAK2/STAT3, MAPK, and PI3K—with insulin in the placenta." (PMID 40725173, 2025). "The loss of JAK2 in specific tissues has been associated with resistance to diet-induced metabolic stress and protection against insulin resistance and inflammation." (PMID 37701031, 2023). "Despite the lack of difference in AKT signalling in the tissues examined, our data suggests a protective effect of macrophage Jak2-deficiency on HFD induced systemic insulin resistance along with reduced circulating glucose and insulin levels." (PMID 28794431, 2017). "Because M1-polarized macrophages are implicated in the development of insulin resistance, we examined an adipose tissue gene expression profile to test whether Jak2 influences the polarization of adipose tissue macrophages." (PMID 40801626, 2025). "JAK2 is associated with Aβ-induced hepatic insulin resistance." (PMID 38396891, 2024). "Mice deficient in JAK2 have lipolysis and impaired insulin resistance." (PMID 36903257, 2023). "For instance, JAK2 deficiency in either hepatocytes, macrophages or adipocytes confers resistance to diet-induced metabolic stress and protects against HD-induced metaflammation and insulin resistance." (PMID 32413585, 2020). "Given the importance of Stat3 in mediating Jak2-driven insulin resistance and inflammation in obese mice, we generated control (Lyz-Cre/Stat3+/+) mice and mice with macrophage cells lacking functional Stat3 alleles (Lyz-Cre/Stat3−/−)." (PMID 40801626, 2025). "The activation of JAK2 is correlated with the emergence of insulin resistance, and the depletion of JAK2 in adipocytes boosts insulin sensitivity in the liver." (PMID 40271123, 2025). "As an upstream target of FOXO4, IL6/STAT3 signaling activation promotes insulin resistance in adipose tissue and muscle, and JAK2/STAT3 activation induces insulin resistance in HepG2 cells." (PMID 41573199, 2025). "Pelargonic acid vanillylamide (PAVA) alleviates NAFLD by exhibiting anti-inflammatory effects and improving insulin resistance mediated by the Janus kinase 2 (JAK2)/signal transducer and activator of transcription 3 (STAT3) pathway." (PMID 39281271, 2024). "The reduced phosphorylation of JAK2 and STAT3 in LEPTIN deficient pig livers led to hepatic insulin resistance and increased fat synthesis marked by activation of SOCS3 and SREBP-1c, respectively, further confirms the value of the pig model." (PMID 37705071, 2023). "PRL and PRLR are related to fat metabolism and promote insulin resistance by activating the Janus kinase 2/signal transducer and activator of transcription 5 (JAK2/STAT5) signaling pathway and increasing triglyceride deposition." (PMID 36993818, 2023). "Amyloid-β protein can lead to insulin resistance as well as the development of T2DM through the activation of the JAK2/STAT3/SOCS1 pathway." (PMID 34991691, 2022). "The regulation of the JAK2/STAT3 pathway in the skeletal muscle of patients with type 2 DM is closely related to the occurrence of insulin resistance, and the phosphorylation of JAK2 and STAT3 can increase the incidence of glucose tolerance loss or DM." (PMID 35563546, 2022). "There are studies that have reported that Aβ induces hepatic insulin resistance by activating JAK2/STAT3/SOCS-1 signaling pathway and have implications on resolving insulin resistance and T2DM." (PMID 34991691, 2022). "The pro-inflammatory cytokine, IL-6, is a plausible mechanistic link between chronic inflammation and glucose intolerance/insulin resistance via the IL6/Jak2/Stat3 axis." (PMID 34943061, 2021).